MUC1 (mucin 1, cell surface associated)
Diseases named in the same sentence as MUC1 in open-access papers (continued):
Sharing a sentence is not in itself a finding about the gene and the disease.
tumor (continued). "Third, MUC1 is an interesting tumor-specific epitope; the epitope with the sequence GVTSAPDTRPAPGSTAPPAH was found repeated 20 to 150 times in the extracellular domain of the transmembrane glycoprotein Mucin1 (MUC1) and constitutes the so-called “variable number of tandem repeats region (VNTR)”." (PMID 37896984, 2023). "Reverse transcription-polymerase chain reaction (RT-PCR) of tumor associated mRNA such as carcinoma embryonic antigen (CEA) mRNA and mucin type 1 (MUC1) mRNAs was also demonstrated having the potential to identify a small number of tumor cells in histologically negative LN from NSCLC patients." (PMID 35159091, 2022). "Therefore, we can draw the hypothesis: MUC1 increases the uptake of glucose and the production of lactate through the HIF-1α signaling pathway, so that tumor cells can survive under hypoxic conditions." (PMID 35879749, 2022). "In studies of the Eo771/MUC1 GEMM TNBC, treatment with GO-203 also resulted in (i) downregulation of PD-L1 expression, (ii) activation of CD8+ T cells in the TME, (iii) induction of TILs effective in killing Eo771/MUC1 tumor cells and (iv) inhibition of Eo771/MUC1 tumor growth." (PMID 35897789, 2022). "•Combined therapy with MUC1 mRNA nanovaccine and anti-CTLA-4 mAb could reduce immunosuppressive TME, increase the infiltration of CD8+ T cells into tumor sites, and enhance anti-tumor cytotoxic T-lymphocyte activity when compared with each monotherapy." (PMID 34875483, 2022). "In addition, although GSDME−/− tumour cells lost the resistance to digestive enzymes, re-expression of exogenous MUC1 or MUC13 largely restored their resistance, and the co-expression of MUC1 and MUC13 achieved the greatest resistance." (PMID 35292781, 2022). "Additionally, when the tumor-bearing MUC1 existed, DCs produced excessive IL10 rather than IL12, even after being stimulated by LPS." (PMID 35883508, 2022). "Therefore, regarding MUC1, MUC2, MUC5AC, and MUC6, the most important point seems to be represented by the simultaneous and the correct use of all four of these mucins, and the integration of their expression pattern with tumor morphology." (PMID 35583805, 2022). "In conclusion, combination treatment with anti-CTLA-4 mAb and MUC1 mRNA nanovaccine could increase the infiltration of CD8+ T cells into tumor sites and enhance anti-tumor cytotoxic T-lymphocyte activity by reducing immunosuppressive TME and inhibiting tumor-promoting STAT3 signaling pathway." (PMID 34875483, 2022). "In the hypoxic condition, MUC1 promotes the recruitment of HIF-1α and p300 to the promoter region of glycolysis genes, upregulates the expression of glycolysis-related genes, increases glucose uptake and lactate production, and assists tumor cells to survive in hypoxic environments." (PMID 35879749, 2022). "Moreover, decreased toxicity may be related to the optimal tumor specificity and T-cell homing, whereas mouse models of BRCA show that CAR T-cells target both transmembrane glycoprotein mucin 1 (MUC1) and human epidermal growth factor receptor 2 (HER2)." (PMID 35883508, 2022). "Similarly, MUC1 was significantly different between primary tumours and normal tissues (p value = 0.0298)." (PMID 35879749, 2022). "The treatment of HzMUC1-MMAE does not affect MUC1 protein levels in xenograft tumor tissues." (PMID 36572921, 2022). "Since the discovery of tumor-specific antigens is not always a feasible task, researchers have suggested targeting the tumor-specific glycoforms (called T, Tn, or sialyl Tn glycoforms) of commonly known TAAs (such as MUC1)." (PMID 36483567, 2022). "MUC1 oligomerization inhibitor blocks BC tumor growth, dependent and independent of estrogen." (PMID 35248049, 2022). "Considering that the immunosuppressive tumor microenvironment is one of the challenges that must be overcome in CAR-T therapy, a strategy for remodeling it could be CAR-T cells’ anti-MUC1 derived from HMFG2 antibody and expressing the costimulatory receptor TR2.41BB." (PMID 35158915, 2022).
tumor (continued). "A lack of co-stimulatory and co-inhibitory MUC1 activities might particularly impact patients with advanced tumor stage and cancer-affected lymph nodes." (PMID 35406491, 2022). "Lastly, we report that high-MUC1 PDA tumors respond to TGF-β neutralizing antibody in vivo showing significantly reduced tumor growth while low-MUC1 tumors do not respond to TGF-β neutralizing antibody further confirming our hypothesis." (PMID 35237602, 2022). "Beyond that, the tumor angiogenesis inhibitor mVEGF165b monoclonal antibody and the COX pathway inhibitor indomethacin may also be ideal immunization adjuncts for enhancing the immune efficacy of MUC1-based BRCA subunit vaccines." (PMID 35883508, 2022). "Moreover, for single treatments with D, RA, Erl, X, and I, we detected comparably low or even a complete lack of toxicity in either MUC-1 alone (for D and Erl) or both tumor models (for I)." (PMID 34439352, 2021). "It has been proven that MUC-1-protein-functionalized GNPs serve as a powerful macrophage activator, promoting the release of TNF-α, IL-6, IL-10, and IL-12 on peritoneal macrophages, resulting in predominant M1 polarization, which showed a promising prospect as a tumor vaccine." (PMID 34572503, 2021). "In addition, polymorphic epithelial mucin (MUC-1) was a kind of high molecular weight glycoprotein, which had abnormal expression in epithelial cell-derived malignant tumors and played an important role in tumor growth, invasion, development and metastasis." (PMID 34522164, 2021). "Furthermore, the predictive value of MUC1 was similar among patients with low recurrent risk, such as CA199 level <37 U/ml, tumor size ≤5 cm, without lymphatic metastasis, without vascular invasion and TNM stage I." (PMID 34729096, 2021). "Furthermore, the prognostic significance of MUC1 was reconfirmed in the ICC subgroups with low recurrent risk, such as CA199 level <37 U/ml, Tumor size ≤5 cm, without lymphatic metastasis, without vascular invasion and TNM stage I 29,40." (PMID 34729096, 2021). "One reason for the stronger observations obtained for tumor-specific markers (CEA and HE4 mRNAs) may be the fact that EOC CTCs are heterogeneous and epithelial markers (i.e. EPCAM and MUC1 mRNAs) may not represent all parts of the tumor." (PMID 34006887, 2021). "Furthermore, MUC1-specific CAR-T cells significantly increased secretion ofIL-2 (597.5 ± 38.89 pg/mL, 15-fold), TNF alpha(359 ± 1.41 pg/mL, 6-fold) and IFN-γ (182 ± 9.89pg/mL, 9-fold) in response to MCF-7, anotherMUC1 positive tumour cell line." (PMID 32347044, 2021). "In this regard, Mei and colleagues have recently proposed mucin-1 (MUC-1) as a target for CAR-T cells based on the higher expression of this protein by tumor cells, compared to non-neoplastic tissue and the effective cytotoxicity of MUC-1 CAR-T cells in vitro and in vivo." (PMID 33804419, 2021). "For example, it has higher tumor specificity and affinity with an increased number of binding sites, reduced binding to shed MUC1 from colon and pancreatic carcinoma, no binding to peripheral blood mononucleated cells, stronger ADCC, and rapid internalization compared to other antibodies." (PMID 33167508, 2020). "Although reduction in tumor growth was limited, simultaneous administration of a combination of three bsAbs (M × 3, M × 28 and M × 2 bsAb) with peripheral blood mononuclear cells (PBMCs) or T-LAK cells in vitro showed higher cytotoxicity against MUC1-expressing bile duct carcinoma cells." (PMID 33167508, 2020). "Therefore, antibodies against tumor associated MUC1 are more likely to bind to the antigen on the surface of tumor cells and not MUC1 on the surface of normal cells." (PMID 33167508, 2020).
tumor (continued). "Moreover, anti-CA125, anti-HER2/neu, anti-MUC1, anti-EGFR mAb treatment can circumvent the tolerance to self-antigens expressed on tumor cells as shown by the increase of the frequency of CD4+ and/or CD8+ T cells recognizing peptides derived from the target molecule in cancer patients." (PMID 31494742, 2019). "Since indomethacin treatment did not enhance the anti-tumor activity of MUC1 vaccine, we hypothesized instead that indomethacin acts on tumor cells to render them more sensitive to immune-mediated killing." (PMID 31693710, 2019). "Moreover, BBiApt selectively enhanced the immune cytotoxicity against the MUC1-positive tumor cells, but not that against the MUC1-negative control cells in vitro." (PMID 30699986, 2019). "The levels of MUC1 immunostaining did not correlate with tumor grade or stage." (PMID 29987260, 2018). "In addition, Siglec-9 also binds to tumor-produced mucins such as MUC1 to lead negative immunomodulation." (PMID 29342882, 2018). "Altogether, these findings suggested that hSiglec-9-hIg2 may be a medical agent against the tumor expressing MUC1 without side effects on the immune system." (PMID 29342882, 2018). "Unfortunately, mAbs targeting MUC1 have failed to inhibit tumor growth in cancer patients." (PMID 29857542, 2018). "Thus, MUC1 does not require presentation by MHC molecules to be recognized for antibody-mediated tumor destruction." (PMID 29415891, 2018). "However, tumor recurrences at early time points from mice treated with TAG72-BBζ CAR T cells showed a dramatic reduction in TAG72 expression, while maintaining expression of MUC16 and MUC1." (PMID 30510550, 2018). "More recently, a clinical trial with the MUC1 100 mer peptide plus Hiltonol adjuvant enlisted a panel of new human anti-MUC1 antibodies that recognized the common PDTR minimal epitope with high affinity and exquisite in vitro anti-tumor effect and in vivo safety in human donors were reported." (PMID 29857542, 2018). "Consistent with the reciprocal expression of WT1 and MUC-1, the remaining six blastemal-predominant tumours that all lacked WT1-negative epithelial structures were devoid of immuno-reactivity for MUC-1 in the examined sections, indicating the absence of UB-like structures." (PMID 29040332, 2017). "Thus, these CAR T cells normally did not bind to glycosylated MUC1, but they specifically recognized the Tn glycoform of MUC1 on tumor cells in this case." (PMID 29312360, 2017). "Downregulation of NudCD1 in tumor cells that showed a high expression of the protein resulted in a down-regulation of some oncogenic genes such as CTSL, MMP15, uPAR, VEGF, COX-2, S100A4, MUC1, MDM2 and RAC110 and an increase of the resistance to 5-fluorouracil-induced apoptosis." (PMID 29021621, 2017). "Since the STn glycan decoration is more frequently found on the surface of carcinomas than the Tn glycan, the binding of MUC1 carrying STn to MGL may be more physiologically relevant and may be in part responsible for some of the characteristics of STn expressing tumours." (PMID 28414807, 2017). "In addition, EGFR, Mucin-1 (MUC1), and integrin beta-4 (ITGB4), which promote tumor growth and metastasis, may be bad prognostic factors in this tumor." (PMID 29282096, 2017). "The study could not evidence any prominence for a particular MUC1 epitope but instead showed that multiplicity of the response both against MUC1 and other tumor antigenic determinants, including predicted neo-epitopes was beneficial for the patient." (PMID 28923084, 2017). "We demonstrate here that over-expression of aberrant MUC1 glycoform amplifies the inflammatory signal induced by AOM/DSS treatment and establishes a positive regulation of inflammatory cytokines, mediated by p65 and EzH2, which positively controls tumor growth and progression." (PMID 29285251, 2017).
tumor (continued). "Based on these observations and a previous report demonstrating MUC1 expression to be independent of microsatellite status, it can be suggested that MUC1 may not be a prominent player in the serrated pathway of neoplasia." (PMID 27705923, 2017). "Since gal-3 increases the endocytosis of MUC1, integrin β1 and CD44, high levels of sTn on the tumor cell surface might be a mechanism to block gal-3-mediated endocytosis, thus increasing the stability of anti-apoptotic molecules and therefore, chemotherapy resistance." (PMID 27835877, 2016). "This may favor recognition of MUC1 neoantigens that were not exposed prior to the tumor-bearing state." (PMID 26788922, 2016). "Consistently, Muc1-silenced TAMs could not enhance self-renewal ability, as reflected by a lower number of tumor spheres formed." (PMID 27276704, 2016). "Therefore, even if MUC1 is not a direct initiator of neoplastic transformation, it plays a key role in aggravating inflammatory conditions that create a pro-tumor microenvironment, accelerating tumor growth and metastasis." (PMID 27754373, 2016). "Knockdown of FRA-1 significantly impacted tumor growth in vivo, further supporting the hypothesis that a novel MUC1: FRA-1 axis contributes to the aggressiveness of PDAC." (PMID 27220889, 2016). "Moreover, although there was not a significant correlation of MUC1 positive with tumor size, tumor differentiation, and clinical stage, it still had the tendency toward higher expression in advanced stage of cancer." (PMID 27190429, 2016). "We could not detect MUC1 expression in patient #2, which might be attributable to a relatively low level of tumor load." (PMID 27825118, 2016). "Earlier attempts at immunization with nonglycosylated MUC1 were not successful as mice failed to produce enough anti-tumor cytotoxic T lymphocytes (CTL) and IgG due to lack of similarities between nonglycosylated and tumor-associated, aberrantly glycosylated MUC1." (PMID 27472370, 2016). "Surprisingly, direct admixture of MUC1-expressing tumor with MUC1-hyperimmune T-cells could not prevent tumor outgrowth or MUC1 immunoediting, whereas ex vivo activation of the hyperimmune T-cells prior to tumor admixture rendered them curative." (PMID 26788922, 2016). "We hypothesized that MUC1 peptides could be optimized, relying on heteroclitic optimizations of potential anchor amino acids with and without tumor-specific glycosylation of the peptides." (PMID 27367740, 2016). "Thus, we chose to incorporate MUC1 and EMA by well-based RPPA to the existing tumor panel." (PMID 26022333, 2015). "In contrast, CTB conjugated MUC1 have no therapeutic efficacy in MUC1+ B16 tumor bearing mice." (PMID 26417929, 2015). "Likewise, core 2 O-glycans of MUC1 from bladder tumors are modified with poly-LacNAc, which allows them to bind to galectin-3 and hamper the access of NK cells to the TNF-related apoptosis-inducing ligand present in the tumor cells surface." (PMID 26161361, 2015). "This also showed cytoplasmic or membranous expression of MUC-1, (Abcam, Ab696-250, 1:100) predominantly in the deeper aspect of the tumour, but did not stain for MUC-2 (Novocastra, NCL MUC2, 1:100), MUC5 (Novocastra, NCL MUC5, 1:100) or MUC-6 (Novocastra, NCL MUC6, 1:100)." (PMID 26589730, 2015). "However, our data indicated that MUC1+B16 tumor cell manly intracellular express MUC1 but not the on-membrane expression." (PMID 26417929, 2015). "MUC1 acts as an oncogene to promote tumor formation and progression by regulating multiple proliferation-promoting signaling pathways; however, whether MUC1 mediates Smad3 signaling in cancer cells has not previously been reported." (PMID 25714018, 2015). "In light of the results presented in this study, including the demonstrated tumor specificity of MUC1 SP, we propose further efforts toward targeting cell-bound MUC1-positive tumors using anti-MUC1 SP antibodies, specific to the cell-bound, rather than the soluble MUC1." (PMID 24416403, 2014).
tumor (continued). "Eight patients had extensive analysis of their PBMCs for tumor-specific T-cell responses, and six of these eight patients developed T-cells specific for multiple tumor-associated antigens that were not included in the vaccine, such as PAP, MUC-1, PSMA, and PSCA." (PMID 25506582, 2014). "Since the extracellular domain of MUC1 protein core is primarily made of the tandem repeats, it is possible that the aptamer MA3 may recognize the MUC1 structure exposed on the surface of MUC1-expressing tumor cells." (PMID 22384115, 2012). "Because the immunological status of MUC1.Tg mice injected with tumor cells expressing MUC1 has not been thoroughly characterized, we compared T cell subpopulations in B6 and MUC1.Tg mice, particularly the CD4+ effector T cells and Treg cells that infiltrated the tumor." (PMID 23028615, 2012). "In the present study, we tested MUC1 expression in cell clusters and in a nude mouse xenograft model, and found medium to strong tumor expression for all three cell lines, indicating that cancer cells do not lose MUC1 expression in passing from in vitro cell clusters to an in vivo animal xenograft." (PMID 24212784, 2011). "In addition, immunization of human MUC1 transgenic mice, where MUC1 is a selfantigen, with the VLP vaccine induced MUC1-specific CTL, delayed the growth of MUC1 transplanted tumors and elicited complete tumor rejection in some animals." (PMID 21773041, 2011). "Moreover, the Apt-NPs enhanced the PTX delivery to the MUC1-positive tumor cells while showing no efficacy towards the control cells." (PMID 21912664, 2011). "Moreover, whereas pharmacologically mediated disruption of the Δψm was accompanied by attenuation of tumor phenotype, it had no impact on MUC1 levels." (PMID 21966455, 2011). "However, MUC1-pep-STn also induced IgG2a antibodies but no tumour protection was observed in mice immunised with this immunogen." (PMID 19436292, 2009). "However, in many experimental studies mannan mixed with MUC1 FP failed to induce the necessary immune responses and tumour protection to have any impact on tumour cell growth in mice." (PMID 16776849, 2006). "In contrast, a fusion protein comprising rapLRI and wild-type scFv 17W could not be purified to homogeneity and did not exhibit any cytotoxic activity towards MUC1+ tumour cells." (PMID 15150594, 2004). "Although anti-MUC1 responses are frequently detected in patients with advanced and progressing adenocarcinomas, activation of immunological effector cells is obviously not sufficient to protect against tumour progression in vivo." (PMID 12966437, 2003). "Nevertheless, whether MUC1 directly or indirectly influences ABC transporter expression in ccRCC remains to be investigated, especially as previous studies have identified MUC1-mediated transcriptional and non-transcriptional mechanisms depending on the tumor type." (PMID 38254882, 2024). "In conclusion, it was determined that CA 15–3 in serum could be detected more sensitively rather than MUC-1 in tissue by biosensor and that the biosensor allowed the CA 15–3 tumor biomarker to be detected even at lower concentrations in serum samples in this study." (PMID 39031228, 2024). "Thus, the proportion of tumor samples positive with EGFR and MUC1 was estimated to be 97.5%, which indicated that a large population of LUAD patients could potentially benefit from EGFR-MUC1 dual-targeting therapies." (PMID 39664199, 2024). "Notably, we found that the ductal cell markers and epithelial cell-specific markers reported previously, such as EPCAM, KRT18, SOX9, KRT19, MUC1, and FXYD3, were commonly expressed in the majority of clusters except for cluster 17, confirming tumor cell identity." (PMID 37324492, 2023).